FRG1 (FSHD region gene 1)
Diseases named in the same sentence as FRG1 in open-access papers (continued):
Sharing a sentence is not in itself a finding about the gene and the disease.
cancer (8 papers, 2017 to 2025). A tumor composed of atypical neoplastic, often pleomorphic cells that invade other tissues. "Another whole-exome sequencing study, done in six follicular thyroid cell lines, reported a mutation in the FRG1 gene in cancer cell lines." (PMID 36329016, 2022). "Our preliminary analysis showed that FRG1 mRNA expression is associated with overall survival (OS) in certain cancers, but the effect varies." (PMID 34795329, 2021). "HPF1, RPL34, and EXOSC9 were the most common genes present in FRG1 associated pathways across the cancer types." (PMID 34795329, 2021). "Very few reports have shown an indirect association of FRG1 with cancer." (PMID 36329016, 2022). "GEPIA-based analysis revealed lower expression of FRG1 transcripts in cancer patients (n = 1085) compared to normal (n = 291)." (PMID 36329016, 2022). "Collectively, our study highlights the therapeutic potential of anti-GM-CSF therapy in cancer samples with low FRG1 expression." (PMID 36329016, 2022). "We observed a significant downregulation of FRG1 levels in cancer patient samples compared to the normal tissue." (PMID 36329016, 2022). "Out of 194 cancer tissues, 57 indicated (29%) high FRG1 expression (AS: 7–8), 106 indicated (55%) moderate expression (AS: 3–6), and only 31 showed (16%) low level of FRG1 (AS: 1–2)." (PMID 36329016, 2022). "Alternatively, other genes which are also altered in cancers conceal the analysis of the effect of FRG1 on the OS." (PMID 34795329, 2021). "Kaplan-Meir survival analysis was performed to determine the effect of FRG1 mRNA expression on the OS across the seven most frequent cancer types." (PMID 34795329, 2021). "There aren’t many studies focusing on FRG1, hence we wanted to perform a comprehensive study in multiple cancer types to elucidate a concreate role of FRG1 in predicating the OS of cancer patients." (PMID 34795329, 2021). "Common genes which were part of the FRG1 related pathways in different cancers were experimentally validated." (PMID 34795329, 2021). "FRG1 affected the proliferation, migration, invasion, and angiogenic potential of cancer cell lines and the expression of G-CSF and MMP106." (PMID 34795329, 2021). "FRG1 expression was decreased in PCa tissues and that affected the migration and invasion of cancer cells." (PMID 34386035, 2021). "We chose the top seven cancer types with the highest incident rates; studies in other cancers can give a more in-depth understanding of the FRG1 pathway." (PMID 34795329, 2021). "From the top 20 genes correlated with FRG1 across cancer types, we found that three genes (HPF1, RPL34, and EXOSC9) were common." (PMID 34795329, 2021). "In conclusion, our study highlights the role of FRG1 in the survivability of cancer patients in tissue-specific manner and the use of multigene models in prognosis." (PMID 34795329, 2021). "Overall, the data suggest that FRG1 affects the survival in cancers but the extent of the effect is tissue specific." (PMID 34795329, 2021). "In conclusion, this study has clearly shown the role of FRG1 in predicting the survivability of cancer patients." (PMID 34795329, 2021). "Subsequently, inference was drawn from Oncomine and Kaplan–Meier plotter analysis, for FRG1 expression in different cancers." (PMID 28947680, 2017). "Our research group, for the first time, showed reduced expression of FRG1 in cancer tissues." (PMID 34795329, 2021). "We first determined the genes positively correlated with FRG1 using multiple databases in different cancer types, based on this hypothesis." (PMID 34795329, 2021). "In our model we found EXOSC9 to be highly correlated with FRG1 in multiple cancer types." (PMID 34795329, 2021). "Role of FRG1 in survival of cancer patients is not clearly understood." (PMID 34795329, 2021). "We first elucidated the role of FRG1 alone in the OS in multiple cancer types." (PMID 34795329, 2021).
cancer (continued). "Additionally, we wanted to determine the general trend of FRG1 expression in tumors, so we took various cancer types and compared expression with its uninvolved counterpart." (PMID 28947680, 2017). "FRG1 in conjunction with other genes may affect the survival of cancer patients." (PMID 34795329, 2021). "We hypothesized that FRG1 expression level could affect the functionality of the correlated genes or vice versa, which might mask the effect of a single gene on the OS analysis in cancer patients." (PMID 34795329, 2021). "Our preliminary analysis did not indicate the robust effect of FRG1 on overall cancer survival in all cancer types." (PMID 34795329, 2021). "In cancer types such as breast, lung, and liver, the difference in FRG1 expression level did not affect OS significantly." (PMID 34795329, 2021). "We chose HEK293T cells to test the oncogenic effects of FRG1, as these cells were not derived from cancer." (PMID 28947680, 2017).
myopathy (2 papers, 2016 to 2021). A disease of the muscle in which the muscle fibers do not function properly. "Similarly, the mechanism by which increased expression of FRG1 leads to myopathy is not understood." (PMID 26942723, 2016).
neurodevelopmental disorder (1 paper, 2021). A behavioral and cognitive disorder with onset during the developmental period that involves impaired or aberrant development of intellectual, motor, or social functions. "This suggests a possible implication of FRG1 in neurodevelopmental disorders." (PMID 34976023, 2021).
FRG1 also shares sentences with these, for which no sentence is quoted: adenocarcinoma (1 paper); Breast Invasive Carcinoma (1); colon adenocarcinoma (1); essential thrombocythemia (1); infection (1); liver cirrhosis (1); Lung Squamous Cell Carcinoma (1); metastasis (1); oral cavity cancer (1); oral cavity tumor (1); ovarian carcinoma (1); thyroid cancer (1).